RETN (resistin)
Diseases named in the same sentence as RETN in open-access papers (continued):
Sharing a sentence is not in itself a finding about the gene and the disease.
diabetes (continued). "Taking most of the factors associated with PE and adjusting for these potential confounding variables (age, parity, BMI, family history of diabetes and preeclampsia), adiponectin and resistin were found to be significant and better predictors of PE than leptin and visfatin." (PMID 33014422, 2020). "The present studies identify resistin as a potential mediator of that phenomenon by demonstrating increases in resistin concentration in the fetal circulation in pregnancies complicated by diabetes and inhibition of mitochondrial biogenesis and metabolism by resistin in the placenta." (PMID 32762639, 2020). "Increased exposure to resistin may contribute to mitochondrial dysfunction and aberrant energy metabolism characteristic of offspring exposed to diabetes in utero." (PMID 32762639, 2020). "In addition to cord blood resistin concentration being higher in pregnancies complicated by diabetes, a positive correlation with maternal blood glucose levels was found." (PMID 32762639, 2020). "Additionally, ABA reduced plasma levels of leptin and resistin, two notable adipokines tied to the diminished uptake of glucose in diabetes and impaired IRS-1 signaling." (PMID 32591558, 2020). "Models 1, 2, 3 and 4 included adiponectin, leptin, resistin and visfatin respectively as predictors whiles controlling for confounding factors like age, parity, BMI, relative with hypertension, and family history of diabetes and preeclampsia." (PMID 33014422, 2020). "The association between serum resistin levels and CKD in diabetes is also unclear." (PMID 32130282, 2020). "Likewise, other molecules including C-peptide, resistin, and C-cystatin also showed significantly lower levels (P < 0.05) in diabetes individuals taking metformin monotherapy compared to those that are under Glipizide monotherapy." (PMID 31178745, 2019). "How diabetes induces and Serca2a reduces resistin expression in cardiomyocytes and whether this is regulated at the transcriptional level is currently unknown." (PMID 30353146, 2018). "Finally, we measured the concentrations of secreted adiponectin and resistin, known as the representative adipocytokines involved in diabetes." (PMID 30294680, 2018). "Given the deleterious effects of aberrant resistin expression in diabetic hearts, measures to lower and normalize its levels may constitute a reasonable mechanism to mitigate diabetes-induced cardiomyopathy." (PMID 30353146, 2018). "This had the effect of decreasing the interest of resistin amongst pure diabetes researchers." (PMID 26097512, 2015). "By contrast, her aberrantly high expression of the transcript encoding the myeloid-secreted adipocytokine resistin was not prima facie consistent with her mid-range low-density lipoprotein cholesterol or the absence of any signs of diabetes." (PMID 26391122, 2015). "To understand the mechanism underlying the effects of ASCs on CAIA, we examined the serum levels of five cytokines (IL-15, IL-1α, IL-6, IL-7, and TNFα), five diabetes-related hormones (resistin, GIP, GLP-1, ghrelin, and leptin), and adiponectin using multiplex immunoassays." (PMID 26210906, 2015). "This view has been supported by the findings that plasma resistin levels were correlated with the risk of developing hypertension over a 14 year follow up of 872 women without previous history of hypertension or diabetes." (PMID 26617526, 2015). "Of the diabetes biomarkers measured, only resistin was affected by a WD×ART interaction." (PMID 25386661, 2014). "Human resistin is also a potential mediator of diabetes and cardiovascular disease." (PMID 24465803, 2014). "Thus, based on the results of the present study, it can be observed that resistin can serve as one of the potential biomarkers for periodontitis with other systemic diseases such as diabetes and cardiovascular diseases." (PMID 24692844, 2014).
diabetes (continued). "Conditions of low-grade systemic inflammation, such as diabetes and atherosclerosis, may induce macrophage expression of resistin and increase circulating levels, independently of metabolic changes." (PMID 22203832, 2012). "Despite the quite promising data from rodent studies, human data did not consistently confirm the association of resistin with insulin resistance, diabetes, and obesity." (PMID 22203832, 2012). "Also, it has recently shown that the levels of resistin are correlated to those of leptin and that both these adipokines induce increased procoagulability in diabetes mellitus." (PMID 22745767, 2012). "The role of resistin in diabetes remains a matter of debate." (PMID 21676224, 2011). "The combined effect of either diabetes or hypertension and high serum resistin was also assessed." (PMID 19922611, 2009). "Given that elevated resistin levels have been observed in patients with diabetes, it is proposed that resistin may play a key role in the development of T2D-related complications by contributing to IR, promoting vascular injury, and consequently, vascular disease." (PMID 40283140, 2025). "Our study has confirmed the results of other researchers that administration of CoQ10 in rats led to reduced serum TNF-α levels, which may have been attributed to CoQ10’s declining effects on resistin levels which are generally heightened in patients with diabetes." (PMID 38227584, 2024). "In addition, the pattern of resistin concentrations in serum is due to their higher levels in both metabolic healthy groups without a direct connection with BMI, suggesting a link between visceral obesity and diabetes in these healthy young individuals." (PMID 38662716, 2024). "Women who had diabetes during pregnancy had a significantly reduced waist circumference and subcutaneous fat thickness after one year (p < 0.001 and p = 0.05, respectively), as well as significantly higher levels of insulin and ghrelin (p < 0.001) and lower levels of resistin (p = 0.005)." (PMID 38004222, 2023). "Therefore, increased expression of resistin may contribute to impaired placental mitochondrial biogenesis and function, as well as offspring adverse outcomes in pregnancies complicated by diabetes." (PMID 32762639, 2020). "Moreover, a recent study evaluating the usefulness of serum adiponectin quantification for prediction of PE concluded that adiponectin levels were the best prognostic factor (as compared to visfatin, resistin, and leptin), when corrected for BMI, age, parity, and family history of PE and diabetes." (PMID 33321877, 2020). "The regulation and roles of human resistin in diabetes during pregnancy remain unclear." (PMID 32762639, 2020). "In more details, the NAFLD diagnostic panel recommended five markers (diabetes, gender, BMI, triglycerides and cytokeratin-18 (CK18) fragments) and performed better than the NASH diagnostic that included three biomarkers (CK18, adiponectin and resistin) for NASH prediction." (PMID 31163711, 2019). "Similarly, NFATc increased resistin expression in myocytes cultured in low glucose while the NFATc inhibitor VIVIT blocked glucose-induced resistin expression, suggesting that hyperglycemia/diabetes induces resistin expression possibly through NFATc activation." (PMID 30353146, 2018). "However, dual to the complexity in human epidemiology, it’s difficult to address whether resistin is an active player in the development of those pathological conditions especially hypertension in diabetes patients." (PMID 26917360, 2016). "However, the role of resistin in the regulation of BP and the development of diabetes and hypertension remains unclear." (PMID 26917360, 2016). "Further studies over the past 10 years have confirmed that rodent and human resistin have distinct expression patterns, and while the circulating levels of resistin may be increased in diabetes, these increases are likely mediated by different mechanisms in each species." (PMID 26076481, 2015).
diabetes (continued). "These discrepancies may be attributed to substantial population heterogeneity, including variations in resistin’s effects by ethnicity, sex—with stronger associations observed in postmenopausal women—and underlying comorbidities such as diabetes versus non-diabetes populations." (PMID 41347124, 2025). "While elevated resistin robustly predicts acute coronary events in hyperinflammatory states, its association with chronic coronary artery disease severity or hemodynamic parameters is negligible in clinically stable patients without acute inflammation, diabetes, or renal impairment." (PMID 41347124, 2025). "The following variables were shown to be clinically important factors and were included in the final model: the number of pack-years, plasma resistin concentrations, hs-CRP, plasma IL-6 concentrations, eGFR, and the presence of diabetes." (PMID 39635208, 2024). "This study firstly analyzed the relationship between leptin and resistin in T2DM according to novel subgroups, providing promising prospects for precision medicine involving leptin or resistin in diabetes." (PMID 34996484, 2022). "Future studies to determine whether the observed changes in circulating resistin persist in the postnatal period and whether they relate to indices of metabolic dysregulation are needed and are best addressed by longitudinal studies of the children born to mothers with diabetes during pregnancy." (PMID 32762639, 2020). "The results of this study showed that patients with CAD with increased prevalence of diabetes, of older age and having higher waist circumference, SBP, pulse pressure, hs-CRP, iPTH and resistin levels but lower eGFR had high aortic stiffness." (PMID 28806778, 2017). "In conclusion, offspring of women with diabetes in pregnancy exhibit increased ADIPOQ DNA methylation and decreased ADIPOQ and RETN gene expression in SAT." (PMID 28413567, 2017). "Taken together, our data indicate that resistin induces IR and hypertension in mice via a mechanism dependent on TLR4 and RAS, suggesting that resistin is a crucial factor linking diabetes and hypertension." (PMID 26917360, 2016). "In recent studies, a correlation between serum resistin and CRP was demonstrated while investigating patients with diabetes, coronary artery disease, or healthy volunteers." (PMID 19545363, 2009). "Systemic serum analysis of patients undergoing CABG determined raised resistin and CRP levels, whereas adiponectin levels were decreased, this reduction being exacerbated in CAD patients with diabetes." (PMID 16412224, 2006). "The consistent association observed in our study invites the hypothesis that resistin and TNF-α may be interact within the shared inflammatory pathway of periodontitis and diabetes." (PMID 41244040, 2025). "A clinical study reported significantly elevated serum levels of TLR4 and resistin in hypertensive individuals with T2D compared to hypertensive patients without diabetes." (PMID 40283140, 2025). "The literature data revealed that patients with periodontitis and systemic inflammatory diseases such as diabetes had higher resistin levels than healthy people, but not higher than chronic periodontitis patients." (PMID 38533160, 2024). "Only one study has demonstrated that resistin levels are higher in obese women with diabetes than obese women without diabetes." (PMID 35628332, 2022). "Resistin SNV (−420G/C) is located in the promoter region of the RETN gene, and plasma resistin is reported to be highest in GG genotype carrying individuals with diabetes compared to remaining SNV (−420G/C) genotypes." (PMID 35565757, 2022). "Moreover, RETN is involved in the interrelationship between MDD and diabetes, whereby neuroinflammation was reported to be of certain relevance." (PMID 34721734, 2021).
diabetes (continued). "This view is supported by observations that the risk of developing hypertension over a 14 year follow up of 872 women without previous history of hypertension or diabetes positively correlates with plasma resistin levels." (PMID 33679451, 2021). "Only the presence of maternal diabetes reached significance in the regression model, indicating maternal age, BMI, and gestational age did not contribute to the different resistin levels between control and diabetic groups observed here." (PMID 32762639, 2020). "In people without diabetes at the baseline, resistin and RBP4 levels were significant predictors of type 2 diabetes development at 10 years." (PMID 31690939, 2020). "Fetal resistin levels were measured in cord blood from pregnancies with (n = 42) and without maternal diabetes (n = 81)." (PMID 32762639, 2020). "Previous clinical studies have reported a decrease inplasma resistin with TEL in diabetes patients;34 however, neither TEL nor ROSI had any effect on resistin in these invitro models." (PMID 29466880, 2018). "In our study, the racial differences in the distribution of leptin and resistin mirror racial differences in the prevalence of diabetes but not BMI." (PMID 29662629, 2018). "Adjustments for BMI and diabetes did not alter the relative level essentially for adiponectin, resistin, MCP-1 and adipsin." (PMID 28491119, 2017). "Resistin could be used in a multiple panel of clinical and biomarkers to discern patients with diabetes from those with IGT; in OSA patients with BMI >40 resistin together with HbA1C could discern patients with diabetes from those with NGM." (PMID 23497617, 2013). "In line, plasma resistin concentration on admission to the ICU did not correlate to pre-existing diabetes mellitus in the sepsis or non-sepsis patients." (PMID 19545363, 2009). "In addition, RETN is involved in the interrelationship between MDD and diabetes." (PMID 39713769, 2024). "Interestingly, the presence of diabetes did not correlate with plasma resistin concentrations in our study." (PMID 39635208, 2024). "Various hormone-like molecules (adiponectin, leptin, resistin, apelin, visfatin, adipsin, omentin, chemerin, and metrnl) are classified as adipokines that are produced by WAT and play a multifaceted role in numerous diseases, including diabetes, atherosclerosis, CVD, and immune disorders." (PMID 39538244, 2024). "Therefore, it is of interest to document the resistin levels in chronic periodontitis patients (CP) with or without type 2 diabetes mellitus (T2DM) in the gingival crevicular fluid (GCF)." (PMID 35574506, 2021). "Circulating resistin levels are positively correlated with both visceral and subcutaneous adipose depots in women, and are higher in patients with type 2 diabetes than among individuals without diabetes." (PMID 30524378, 2018). "It was difficult to conclude that resistin is a biomarker for diabetes as there are several factors affecting its level, like the inflammatory status of the subjects, including the oral health condition which was not considered in many of the previous studies linking resistin to diabetes." (PMID 29138754, 2017). "However, in individuals with diabetes, resistin levels are not correlated with BMI." (PMID 38794651, 2024). "In fact, we observed a higher, but not significantly, resistin level in relation to maternal hyperglycemia, while Dalcin and coworkers noted the presence of significantly higher values for obese non-diabetes, normal weight diabetes, and obese diabetes groups in relation to the normal weight cohort." (PMID 38612666, 2024). "However, the exact biochemical pathways in mice and humans seem to be very different, and it is not obvious whether resistin plays the same role in the development of diabetes in humans as it does in mice." (PMID 17479165, 2007).
diabetes (continued). "Serum markers like PDGF-BB, IP-10, resistin and PAI-1 levels were significantly increased in the CAD group, therefore representing specific markers for the CAD in the absence of diabetes." (PMID 30674322, 2019). "Trends and significant differences remained for resistin, CRP, insulin and HOMA2-IR among a healthier subgroup of participants that was free from cancer, CVD and diabetes (data not shown)." (PMID 19788754, 2009). "In a subset of mice from the current study (WT and AD groups with the sham surgery), we previously reported that 3xTg-AD females did not display increased plasma levels of other diabetes markers (e.g., insulin, GIP, GLP-1, PAI-1, resistin) or peripheral inflammation." (PMID 35568928, 2022).